TTF1 (transcription termination factor 1)
Diseases named in the same sentence as TTF1 in open-access papers (continued):
Sharing a sentence is not in itself a finding about the gene and the disease.
tumor (continued). "In contrast, almost half of the cases in the non-mucinous group were double-positive for TTF-1 and HNF4α (7/15, 46.7%), and their expression patterns were heterogenous and mutually exclusive within the same tumor (Online Resource 5a)." (PMID 38710944, 2025). "Immunohistochemistry showed tumor cells positive for TTF-1 and negative for p40, confirming the diagnosis of pulmonary adenocarcinoma." (PMID 41018467, 2025). "Immunostaining for CK7, CK20, TTF-1, and Napsin A was negative in the tumor tissues of the stomach, pancreas, and kidney, and as no other primary tumor was detected, it was considered to be metastasis of hepatocellular carcinoma." (PMID 38451411, 2024). "For many tumor entities, immunochemical studies of TTF-1 expression in sizable cohorts are yet lacking." (PMID 39377914, 2024). "In only 1 of them, TTF1 expression was strong and diffuse; this patient had no other oncologic history and the tumor was diagnosed as small cell carcinoma of the breast." (PMID 37306115, 2024). "Tumor sections were stained with hematoxylin and eosin (H&E), and immune-stained for clinically relevant biomarkers, including the primary markers for ADC (TTF1 and Napsina), SCC (P63), as well as LCNEC (CD56, Synaptophysin, Chromogranin)." (PMID 39528952, 2024). "Inour case, the tumor cells were negative for thyroglobulin and TTF-1 but positive forPAX8 and HNF1β." (PMID 39700333, 2024). "In this population, pemetrexed-containing chemoimmunotherapy demonstrated superior anti-tumor efficacy, irrespective of TTF-1 expression." (PMID 39076994, 2024). "Immunohistochemistry revealed that the tumor cells were positive forcytokeratin AE1/AE3, hepatocyte nuclear factor-1-beta (HNF1β) and PAX8 andnegative for thyroglobulin and thyroid transcription factor-1 (TTF-1)." (PMID 39700333, 2024). "SRGN plays a key role in the interaction between tumor and stroma and reprogramming to an invasive and immunosuppressive tumor microenvironment in TTF-1 negative LUAD." (PMID 39684426, 2024). "Histologically, the tumor cells were arranged in sheets with nesting in places and areas of necrosis, showing strong punctate staining for cytokeratin, which is helpful in diagnosing SCLC, and were also positive for TTF-1 and POU2F3." (PMID 38649942, 2024). "Immunohistochemistry showed that the tumor cells were strongly positive for TTF1, NapsinA, EMA and CK7 and negative for CEA and P63, with a low Ki-67 proliferation index." (PMID 38902753, 2024). "The immunohistochemical analysis for TTF‐1 in this study showed that most of tall column‐like tumour cells were negative or weakly positive for TTF‐1, whereas quasi‐circular tumour cells were positive for TTF‐1." (PMID 38616354, 2024). "In addition to the preservation of the histological features, a subsequent analysis of tumor marker expression demonstrated that both ATC spheroids and their corresponding tumors displayed comparable staining patterns for Ki-67, CK19, and TTF-1." (PMID 38500204, 2024). "Immunohistochemically, the tumor cells showed strong punctate staining for cytokeratin, patchy but strong membranous reactivity for LCA and CD43, and positivity for TTF-1 and P63, and CD117 (KIT)." (PMID 38649942, 2024). "Immunohistochemically, no tumor expressed TTF‐1, whereas all tumors exhibited diffuse positivity for p40." (PMID 37974379, 2024). "Immunohistochemical analysis for TTF‐1 showed that 8 of the 15 patients with tall column‐shaped tumour cells showed a negative or weakly positive result for TTF‐1, whereas all the 15 patients with quasi‐circular tumour cells showed a positive result." (PMID 38616354, 2024). "Immunohistochemical detection of the neuroendocrine markers chromogranin A or CGRP as well as the expression of TTF-1 or the absence of p63 that were observed in subcutaneous tumors corroborated the presence of metastatic tumor cells." (PMID 37894963, 2023).
tumor (continued). "The tumor cells were positive for AE1/AE2, calretinin, WT-1, D2-40, HEG1, EMA, BAP1, and MTAP and negative for carcinoembryonic antigen, MOC-31, Ber-Ep4, ER, PgR, TTF-1, claudin 4, and desmin." (PMID 36896044, 2023). "Immunohistochemical analysis of tumor cells is positive for epithelial-derived markers such as CK, alveolar epithelial markers such as TTF-1, NapsinA, and CK7, and negative for mesothelial cell markers such as WT-1, calretinin, D2-40, and CK5/6." (PMID 37194050, 2023). "While IgG4 profiling was not available, other features such as positive stromal TTF-1, S100 protein (neuroectodermal cells), and lack of tumor markers such as CD56 and p63 were found to be distinctive in RT." (PMID 37371786, 2023). "In IHC, the tumor cells were positive for TTF-1 and thyroglobulin, but negative for CK19, HBME-1, Galectin-1 and BRAF (V600E)." (PMID 37544981, 2023). "Immunohistochemical biopsy results revealed TTF-1, Napsin A, and CK7 positivity in the tumor cells." (PMID 35814395, 2022). "Subsequently, we performed immunohistochemical (IHC) assays, the results confirmed that in GNIP1-overexpressing tumors, the expression level of Ki67 was increased while that of TTF1 was decreased, indicating that GNIP1 can promote cell proliferation and tumour growth in vivo." (PMID 36042481, 2022). "The only case expressing TTF1, was an intrapulmonary tumor which has been negative for pan-cytokeratin (patient 5)." (PMID 35864317, 2022). "The tumor cells were positive for p63 and negative for thyroid transcription factor 1 (TTF-1) by immunohistochemistry." (PMID 35168684, 2022). "Core biopsy of left chest wall nodule also revealed poorly differentiated LUAD with tumor cells positive for pan-keratin and TTF-1 and negative for ER, PR, CDX2, WT1, PAX-8, synaptophysin and chromogranin." (PMID 35546239, 2022). "We collected clinical medical records including data on TTF‐1 expression and analyzed the relationship between TTF‐1 expression and programmed death‐ligand 1 tumor proportion score (PD‐L1 TPS), objective response rate (ORR), progression‐free survival (PFS), and overall survival (OS)." (PMID 35808895, 2022). "Our retrospective study collectively showed that TTF-1 immunostaining of tumor cell seemed to be a prognostic marker rather than a predictive marker." (PMID 36614938, 2022). "In all cases tested, the tumor cells were positive for PAX8 (2/2, diffusely in both), GATA3 (4/4, diffusely in two and focally in two), and TTF1 (3/3, focally in two and diffusely in one), and the one (case 3) which was diffusely positive for TTF1 also diffusely expressed GATA3." (PMID 35865471, 2022). "Since the tumor nodules in Rnf43−/−; KrasG12D lungs were positive for duct marker CK19 and negative for pulmonary adenocarcinoma marker thyroid transcription factor 1 (TTF‐1), they are likely to be metastatic PDAC but not spontaneous lung tumor." (PMID 35229994, 2022). "TTF‐1 expression was negative in tumor cells and positive nuclear staining in normal alveolar epithelial cells in eleven of twelve cases." (PMID 34409758, 2021). "Immunohistochemical analyses confirmed the tumor as derived from non-thyroidal tissues, as no immunoreactivity was noted for TTF1, PAX8, thyroglobulin, chromogranin A, calcitonin and CEA." (PMID 32519264, 2021). "In this case, tumor cells were eosinophilic on hematoxylin and eosin (HE) staining, negative for TTF-1, thyroglobulin, and chromogranin A, and positive for PTH on immunostaining." (PMID 33978837, 2021). "In our series, however, two TTF-1-negative cases with the tumor located away from the pleura suggest that epithelium is derived from a larger bronchus." (PMID 34350112, 2021).
tumor (continued). "LADs with no expression of NKX2‐1/TTF‐1 exon 1 were significantly associated with older age (p = 0.0006), no TTF‐1 immunoreactivity (p = 0.0009), and EGFR wild‐type tumours (p = 0.0009)." (PMID 34014042, 2021). "Although most tumors exhibited immunoprofile characteristic for MCC, three tumors were CK20 negative and one rare tumor was positive for TTF1." (PMID 34071045, 2021). "Immunohistochemical analysis showed that the tumor was positive for TTF-1 and P63 (focal) and negative for CK5/6." (PMID 34663408, 2021). "While the tumor lacked staining for TTF-1, which is usually present in pulmonary small cell carcinoma, this marker has been found to be negative in up to 17% of cases." (PMID 34391482, 2021). "Only one tumor (0.7% of pRCCs) was found that histologically resembled thyroid parenchyma, despite being TTF1 and thyroglobulin negative, and was diagnosed as TLF RCC." (PMID 34680535, 2021). "One example of the non-common mechanism of tumor aggressiveness is the dysregulated transport of thyroid transcription factor 1 (TTF-1)." (PMID 33578751, 2021). "The immunohistochemical features of this case were consistent with those of previously reported cases of TL-LGNPPA: the glandular tumor cells exhibited diffuse strong immunoreactivity for TTF-1, but no immunoreactivity for thyroglobulin." (PMID 34941144, 2021). "Immunohistochemically, tumor cells were negative for thyroid transcription factor-1 (TTF-1), negative for thyroglobulin, negative for chromogranin A (positive for normal parathyroid tissue within the nodule), positive for PTH, and positive for parafibromin." (PMID 33978837, 2021). "Microscopic tumor areas that were positive for TTF1 were focally and weakly positive or negative in four cases (cases 3, 7, 9, and 20), and vice versa in the remaining four cases (cases 1, 14, 19, and 21)." (PMID 34829389, 2021). "We noted the expressions of CK5/6 and p63 were evident, while expressions of TTF‐1 expression in the tumor cells were negative in the most cases." (PMID 34409758, 2021). "The tumor cells were positive for CT, CgA, Syn, CD56, and TTF-1 in all 4 cases." (PMID 34838061, 2021). "Immunohistochemical examinations showed that the tumor cells were positive for p63 and p40 and negative for SP-A, TTF-1, chromogranin A, synaptophysin, S-100, and calponin." (PMID 32757102, 2020). "From the cytological point of view, the key to distinguishing these lesions is that in our case, tumor cells showed a three-dimensional configuration, were positive for TTF-1 and napsin-A and negative for P40, but no obvious cilia and goblet cell were found." (PMID 33282636, 2020). "Immunohistochemical staining showed that the tumour cells expressed TTF1, napsin A, and CK7, but not P63, P40, CK5/6, CgA, Syn, CD56, and TG." (PMID 33282636, 2020). "At 12 weeks post‐intratracheal intubation, KP mice developed ADC tumours as determined by the expression of the ADC marker TTF1 and the absence of the SCC marker KRT5 (Fig EV3A–C)." (PMID 32128997, 2020). "The IMP, tTF-NGR (His-tag-tTF1-218-GNGRAHA), is the lead compound of our series of fusion proteins carrying tumor-targeting peptides instead of the transmembrane domain at the C-terminus of truncated tissue factor for induction of tumor infarction." (PMID 32517329, 2020). "The study of dynamics of changes in genomic distribution of TTF‐1 and its co‐TFs, during the transformation of LADC into SCLC, could help clarify its complex roles during tumor progression and differentiation." (PMID 31782890, 2020). "Immunophenotypically, the tumor was positive for vimentin, epithelial membrane antigen (EMA) and negative for CK-pan, CAM5.2, CD31, CD34, smooth muscle actin (SMA), desmin, anaplastic lymphoma kinase (ALK), calponin, TTF-1 and S-100 protein." (PMID 32039736, 2020). "Negativity for TTF-1 and thyroglobulin ruled out the possibility that the tumor is of thyroid origin." (PMID 32756201, 2020).
tumor (continued). "In the remaining two cases (cases 2 and 4), p40‐positive tumor cells did not express TTF‐1, neuroendocrine markers, or CK5." (PMID 30957413, 2019). "Immunohistochemical staining was performed in six PSPs, and we found that some tumor cells were immunopositive for epithelial membrane antigen (EMA) (3/6), thyroid transcription factor‐1 (TTF‐1) (6/6), vimentin (2/6), CD68 (2/6) and cytoskeleton 7 (CK‐7) (4/6)." (PMID 31131992, 2019). "We noticed a weak positive correlation of irisin expression level with TTF-1 in tumour cells (r = 0.21, p < 0.0001) and a weak negative correlation with p63 (r = −0.20, p < 0.0001)." (PMID 31614634, 2019). "Endobronchial ultrasound-guided transbronchial needle aspiration (EBUS-TBNA) revealed that the tumor was adenocarcinoma, but immunohistochemical stain for TTF-1 was negative." (PMID 30999697, 2019). "The tumor cells were positive for cytokeratin MNF116, cytokeratin 7, TTF1, PAX8 and thyroglobulin." (PMID 31699114, 2019). "Immunostaines for RCC, CD10, CK20, chromogranin A, synaptophysin, TTF-1, thyroglobulin, and transthyretin were negative in the tumor cells." (PMID 30340515, 2018). "Tumor cells were positive for Hep Par-1 and glypican-3, and negative for cytokeratin (CK) 7, CK20, thyroid transcription factor 1 (TTF-1), inhibin, OCT3/4, prostate-specific antigen (PSA), prostatic specific acid phosphatase (PSAP), renal carcinoma marker (RCC), and PAX8." (PMID 30268151, 2018). "IHC analysis of biopsied tumor tissue revealed positive p40 and p63 and negative TTF-1 and napsin A immunoreactivity, confirming a diagnosis of Sq-LC." (PMID 29844868, 2018). "All patients had their tumor positive for thyroid transcription factor 1 (TTF-1), except for a patient whose tumor was not tested." (PMID 30428509, 2018). "In a total of 1027 NSCLC tumor tissue specimen HMB45, MelanA, SOX10, CK5/6, NapsinA, p63, and TTF-1 could be evaluated." (PMID 30205833, 2018). "The mechanisms which control tissue-specific expression of TTF-1, tumor differentiation, and their prognostic significance are not fully understood." (PMID 29079814, 2017). "To exclude the possibility of a distinct subset of KL ADC that may express p63, we further validated SqCC or ADC subtypes in KL tumours by double-staining with two SqCC markers, p63 and CK5, as well as a combination of SqCC and ADC markers, CK5 and TTF-1." (PMID 28548087, 2017). "The tumor contained a 3 mm focus of a lesion staining positive for TTF1 and Thyroglobulin, and negative for RCC marker." (PMID 28249616, 2017). "The tumor showed positive immunostaining for Vimentin, CD31, CK7, D2–40, c-MYC, Ki67, focal positivity for PanCK, and negative immunostaining for Factor VIII, CD34, WT1, CK5/6, Calretinin, EMA, HBME-1, CEA, p63, EpCAM, Bcl-2, TTF1 and Thyroglobulin." (PMID 28810922, 2017). "Therefore, it is interesting to further evaluate the heterogeneity of CTCs in patients with SCLC using known and well established markers, such as TTF-1 and CD56 which are expressed on neuroendoctrine tumor cells." (PMID 28349943, 2017). "The immunohistochemistry showed positive tumor cells with TTF1 and cytokeratin (CK) 7 but negative tumor cells with thyroglobulin and CK20." (PMID 28327204, 2017). "An Immunohistochemistry showed positive tumor cells with TTF1 and cytokeratin (CK) 7 but negative cells with thyroglobulin and CK20." (PMID 28327204, 2017). "Immunohistochemical staining revealed that the large-sized tumor cells were positive for CD20, PAX-5, MUM-1 and BCL-2, and were negative for CD3, CD5, CD43, CD10, CD23, CyclinD1, CD138, CD30, ALK, CD56, MPO, S-100, TTF-1, thyroglobulin and calcitonin." (PMID 28841887, 2017). "Our current case had no history of tobacco smoking, a CT scan and mediastinotomy confirmed the thymic location of the tumor, and immunohistochemistry ruled out the lung phenotype (TTF-1 and CK7 negative)." (PMID 28602157, 2017).
tumor (continued). "Immunohistochemical studies showed positive results for vimentin, actin, and desmin in tumor tissue, whereas other markers including pan-cytokeratin, thyroglobulin, and TTF-1 were negative." (PMID 27080750, 2016). "Immunohistochemical stains performed with appropriate controls on both tumor nodules reveal immunoreactivity for TTF-1 (Thyroid Transcription Factor-1, data not shown), indicating pulmonary primary." (PMID 27597976, 2016). "Our patient's tumor cells were negative for TTF-1 and TG in the renal and skull and meningeal tissues." (PMID 27082575, 2016). "The cytoplasm of tumor cells was strongly positive for synaptophysin, CD56, TTF1, and CK7." (PMID 26801624, 2016). "Immunohistochemical analysis indicated that the tumor was positive for TTF-1 and SYN, but negative for CD5/6." (PMID 25789020, 2015). "Moreover, the nested spindle/ovoid tumor cells among the alveoli were AE1/AE3+, EMA+, CK7-, TTF-1-, PE10-, p63+, CK5/6+, CK10/13+, and vimentin-." (PMID 26205138, 2015). "Immunohistochemical analysis indicated that the tumor was positive for TTF-1, NSE, chromogranin A and Ki-67, but negative for SYN, leukocyte common antigen, p63 and CD5/6." (PMID 25789020, 2015). "In this study, we showed that TTF-1 expression does not have prognostic relevance though correlated significantly with tumor location of SCLC." (PMID 26705222, 2015). "On the other side negativity for TTF-1 does not exclude pulmonary SRCC if the tumor is CK 7, positive." (PMID 24716057, 2014). "The tumor was diagnosed as invading the visceral pleura and immunohistochemical staining showed caudal-type homeobox transcription factor 2 (CDX-2)(+), mucin-1(+), cytokeratin 7 (CK7)(+) and thyroid transcription factor-1 (TTF-1)(−) in the tumor cells." (PMID 24348839, 2014). "In one reported case the tumor was thyroglobulin positive, but the authors did not test TTF-1 or galectin-3." (PMID 23819507, 2013). "At the head and neck unit, our patient underwent a biopsy that showed a cervical lymph node metastasis of a neuroendocrine small-cell carcinoma from pulmonary origin (The immunocytochemical study had demonstrated that tumor cells were positive to synaptophysin, chromogranin, CK7, and TTF1." (PMID 23119202, 2012). "By immunohistochemistry the tumor cells were cytokeratin 7 positive, cytokeratin 20 negative, and TTF-1 negative." (PMID 21559200, 2011). "Also, in addition to positivity of estrogen, progesteron, cerbB-2, gross cystic disease fluid protein-15 (GCDFP-15) and negativity of thyroglobulin, TTF-1, CEA and calcitonin will make possible the differential diagnosis of tumours originated from the breast." (PMID 22933935, 2011). "CD10, vimentin and pancytokeratin positivity, however, in the same tumour areas cells were negative with TTF-1, thyroglobulin and calcitonin." (PMID 22933935, 2011). "The tumor cells demonstrated immunoreactivity for TTF-1, SP-A and lacked expression of GCDFP-15, ER and mammaglobin." (PMID 21167048, 2010). "Alpha-methylacyl-coenzyme A-racemase (AMACR/P504S), calretinin, CD10 and thyroid transcription factor-1 (TTF-1) did not stain any of the three components of the tumor." (PMID 19523243, 2009). "Tumor markers ordered included: CK7, CK20, TTF1, ER, PR, Calretinin, WT1, CA 125, BRST-2, and CEA." (PMID 18036260, 2007). "Immunohistochemically, the metastatic tumor cells were positive for TTF-1 and negative for P40." (PMID 40746613, 2025). "The tumor was positive for TTF-1 and negative for CK20, findings more consistent with SCLC." (PMID 40585617, 2025). "Tumor cells were also positive for TTF1 and negative for CDX2, favoring lung origin." (PMID 39130860, 2024). "Furthermore, our findings suggest that the internal tissue conformation of the TTF-1 positive and negative groups was differently altered, in terms of tumor material components, density and cellular metabolic activity." (PMID 39456114, 2024).